CLCA1 (chloride channel accessory 1)
Description:
May be involved in mediating calcium-activated chloride conductance. May play critical roles in goblet cell metaplasia, mucus hypersecretion, cystic fibrosis and AHR. May be involved in the regulation of mucus production and/or secretion by goblet cells. Involved in the regulation of tissue inflammation in the innate immune response. May play a role as a tumor suppressor. Induces MUC5AC.
Synonyms: hCLCA1; CaCC-1; hCaCC-1; CACC1; CaCC; CLCRG1; GOB5
Tractability: Small molecule: it belongs to a druggable protein family. Antibody: UniProt places it where antibodies can reach, with high confidence; its Gene Ontology location is reachable by antibodies, with high confidence; UniProt predicts a signal peptide or a membrane-spanning region.
Gene: Protein-coding gene on chromosome 1 (86,468,368 to 86,501,400, forward strand). Ensembl gene ENSG00000016490.
Subcellular location: Secreted, extracellular space; Cell membrane
Pathways (Reactome):
Transport of small molecules: Stimuli-sensing channels
Gene Ontology:
Molecular function: chloride channel activity; intracellularly calcium-gated chloride channel activity; metalloendopeptidase activity
Biological process: monoatomic ion transmembrane transport; cellular response to hypoxia; chloride transmembrane transport; chloride transport
Cellular component: plasma membrane; extracellular region; membrane; microvillus; secretory granule; zymogen granule membrane
Genetic constraint (gnomAD): Loss-of-function variants: 49 observed, 69.66 expected, observed/expected ratio (o/e) 0.7, 90% interval 0.56 to 0.89. The upper end of that interval is the gene's LOEUF score, 0.89, which puts it in group 3 of 6, group 1 being the genes least tolerant of losing a copy. Missense variants: 874 observed, 985.32 expected, observed/expected ratio (o/e) 0.89, 90% interval 0.84 to 0.94. Synonymous variants: 338 observed, 361.61 expected, observed/expected ratio (o/e) 0.93, 90% interval 0.85 to 1.02.
Homologues: Orthologues: chimpanzee CLCA1 (99% identical), macaque CLCA1 (92% identical), dog CLCA1 (82% identical), pig CLCA1 (80% identical), rabbit CLCA1 (80% identical), guinea pig CLCA1 (76% identical), mouse Clca1 (75% identical), rat Clca1 (75% identical), tropical clawed frog clca1 (46% identical), tropical clawed frog clca3p (44% identical), tropical clawed frog clca2 (42% identical), zebrafish clca5.2 (38% identical), and 4 more. Paralogues in human: CLCA4 (61% identical), CLCA2 (44% identical).
Diseases named in the same sentence as CLCA1 in open-access papers:
CLCA1 is named in the same sentence as 64 diseases in open-access papers, as found by Europe PMC text mining. Sharing a sentence is not in itself a finding about the gene and the disease. The quoted sentences say what the papers report.
asthma (62 papers, 2010 to 2025). "Other markers previously associated with type 2 inflammation in asthma, including CLCA1, SERPINB2, and SPDEF, were significantly (p < 0.0001) increased in the IL-13 treated HBEC compared to normal HBEC." (PMID 38706568, 2024). "Human CLCA1 is reportedly closely associated with mucus production in the bronchial epithelium of asthma patients." (PMID 33066398, 2020). "CLCA1 (calcium-activated chloride channel regulator 1), which is involved in mucus secretion, has also been linked to asthma." (PMID 33255348, 2020). "We found key asthma-associated genes including the T2-high signature genes of CLCA1, POSTN, and SERPINB2 as well as those not previously asthma-associated (e.g., CST1 and Vanin genes—VNN1–3) to be potentially influenced by aberrant H3K27ac." (PMID 33362848, 2020). "Clinically, CLCA1 has been associated with innate airway immune response, airway inflammation, asthma, and COPD." (PMID 31333624, 2019). "Two of the highest regulated genes were Clca1 (chloride channel accessory 1) and Retnla (resistin like alpha, also known as Relma/Fizz1), both of which are implicated in asthma." (PMID 30233597, 2018). "CLCA1 represents a multifunctional protein and has been linked to various diseases with mucus overproduction, including cystic fibrosis, asthma and chronic obstructive disease." (PMID 29416634, 2018). "In recent years, genetic studies of bronchial epithelial cells have discovered several genes, such as protocadherin 1 (PCDH1), periostin (POSTN), serpin family B member 2 (SERPINB2), and chloride channel accessory 1 (CLCA1), associated with asthma phenotypes." (PMID 28725641, 2017). "Linked to increased mucus production are SPDEF (SAM pointed domain-containing Ets transcription factor) and CLCA1, both also induced by T2 cytokines in the airway epithelium and the latter is also linked genetically to asthma and part of the epithelial T2 signature introduced above." (PMID 33255348, 2020). "Goblet cell gene expression analysis revealed that HDM exposure induced multiple asthma‐associated transcripts, including chloride channel calcium‐activated 1 (Clca1/Gob‐5), mucin 5, subtypes A and C, tracheobronchial/gastric (Muc5ac), intelectin 1 (Itln1), and intelectin 2 (Itln2/B)." (PMID 27621809, 2016). "Because of its involvement in other airway diseases, such as asthma, we hypothesized that Ca2+-activated Cl- channel 1 (CLCA1) was associated with overproduction of mucus in the airways of smokers and COPD patients." (PMID 22731784, 2012). "We previously established that the expression of CLCA1 was associated with asthma pathology." (PMID 22731784, 2012). "Clca1 is a member of the Clca family and modulates the epithelial cell chloride current and participates in the pathogenesis of mucus hypersecretory-associated respiratory diseases, including asthma, chronic obstructive pulmonary disease, cystic fibrosis, and pneumonia." (PMID 35774783, 2022). "Chloride channel regulator 1 (CLCA1) is involved in promoting mucus secretion and regulating innate immune responses in asthma." (PMID 39563781, 2024). "On the other hand, the expression of CLCA1 was found to have a positive correlation with the levels of serum IL-13 in children diagnosed with asthma." (PMID 39176391, 2024). "In conclusion, this study shows that the expression of CLCA1 and IL-13 was positively correlated in pediatric asthma, and that knockdown of CLCA1 attenuated the IL-13-induced decreased activity and apoptosis of bronchial epithelial cells." (PMID 36313877, 2022). "Together, these results suggest that CLCA1 mediates the regulatory effect of IL-13 on pediatric asthma." (PMID 36313877, 2022). "Whilst this study implicates the potential role of CLCA1 in pediatric asthma, additional in-depth investigations into the biological mechanism are still required." (PMID 36313877, 2022).
asthma (continued). "CLCA1 exhibited the greatest fold difference between the asthma children and healthy controls and was therefore selected as the candidate gene for our study." (PMID 36313877, 2022). "CLCA1 is highly expressed in children with asthma and mediates the contributory effect of IL-13 on the occurrence and development of pediatric asthma." (PMID 36313877, 2022). "While this study suggests that CLCA1-mediated IL-13 has a role in the regulation of pediatric asthma, several aspects remain to be improved." (PMID 36313877, 2022). "We found that the expression of CLCA1 and IL-13 were positively correlated in pediatric asthma relative to healthy controls." (PMID 36313877, 2022). "Approximately half of the asthma subjects (n = 22) with consistently high expression of a signature of Type 2 inflammation (SERPINB2, POSTN and CLCA1) were identified as Th2-high asthma, and 20 asthma subjects were identified as Th2-low asthma." (PMID 35550122, 2022). "As demonstrated by others, quantification of expression of the LAE asthma-related genes CLCA1, SERPINB2 and POSTN confirmed they were up-regulated in asthmatics vs controls." (PMID 34233672, 2021). "The type 2 status of asthma was defined by the expression of the type 2 signature genes (CLCA1, POSTN, and SERPINB10) in the epithelial brushings as previously reported." (PMID 33945508, 2021). "Candidate DEGs including SERPINB2, POSTN, and CLCA1 have already been reported to participate in asthma." (PMID 35126350, 2021). "Originally described as a calcium-activated chloride channel, CLCA1 likely functions indirectly in chloride transport and has previously been reported to be up-regulated in asthma." (PMID 32900903, 2020). "We observed interactions between CLCA1 and asthma DERs located downstream and an asthma-SE located upstream encompassing the CLCA2 transcriptional start site." (PMID 33362848, 2020). "Calcium-activated chloride channel (transmembrane protein 16A, TMEM16A) and calcium-activated chloride channel regulator 1 (CLCA1, the human ortholog of mouse CLCA3/Gob-5) have both been linked to mucus hypersecretion in asthma and COPD." (PMID 32637364, 2020). "Remarkably, there was minimal H3K27ac enrichment across the CLCA1 gene in either healthy or asthma BECs suggesting that transcriptional control of CLCA1 requires interactions with distal regulatory elements." (PMID 33362848, 2020). "It is thus possible that the observed induction of CLCA1 in diseased lungs in asthma, cystic fibrosis, and COPD facilitates mucus structure rearrangements similar to the function of CLCA1 in the intestine." (PMID 31570526, 2019). "Some confusing but potentially important observations are that the same CLCA1 acted differently from different types of cancers and the similar asthma studies yielded contradictory observations." (PMID 31871532, 2019). "Different studies have indicated that IL1RL1 is increased in severe asthma and is associated with multiple indicators of TH2-like inflammation, including blood eosinophils, exhaled nitric oxide, epithelial CLCA1 and eotaxin-3." (PMID 30598657, 2018). "In an ovalbumin-induced mouse model of asthma, the murine CLCA1 ortholog was strongly secreted into the airway fluids." (PMID 29610986, 2018). "Heterogeneity in the severe asthma samples was evaluated using the IL-13 disease signature (CLCA1, SERPINB2 and POSTN) and the gene expression marker for steroid response (FKBP5)." (PMID 28045928, 2017). "A persistent disease signature associated with IL-13 (CLCA1, POSTN, SERPINB2) was identified in peripheral airways in treatment-resistant severe asthma." (PMID 28045928, 2017). "In mouse models of both allergic and respiratory virus induced-asthma, CLCA1 (previously known as mCLCA3 or gob-5) expression has been solidly linked to IL-13 driven MCM and controversially linked to AHR, both hallmarks of asthma and COPD." (PMID 26612971, 2015).
asthma (continued). "CLCA1 is a promising therapeutic target for asthma and COPD, as it is the only member of its family to be upregulated in models of IL-13 mediated mucus overproduction, is a secreted protein, is expressed in goblet cells, and associates with mucin granules." (PMID 26612971, 2015). "The expression and production of CLCA1 have been reported to increase in airways during asthma in mouse and man." (PMID 26067998, 2015). "In asthma, the three-gene-mean of periostin, CLCA1 and serpinB2 correlated with FeNO (r = 0.75, p = 0.0002), blood eosinophils (r = 0.58, p = 0.003) and PC20 methacholine (r = -0.65, p = 0.0006), but not total serum IgE (r = 0.33, p = 0.1)." (PMID 23866775, 2013). "The expression of human CLCA1 (hCLCA1) is increased in patients with asthma and COPD in which mucus was excessively produced in the airway." (PMID 23691121, 2013). "MUC5AC protein was detected in airway epithelia, and MUC5AC expression mostly coincided with the expression of CLCA1, as previously reported in asthma." (PMID 22731784, 2012). "Notably, AEC and NEC-derived correlated gene signatures including CCL26, CLCA1 and POSTN were involved in IL-13 signaling, where IL-13 signaling of the airway epithelium is associated pathophysiology of asthma and airway inflammation." (PMID 37438356, 2023). "CLCA1, IL-4, and IL-13 were highly expressed in the serum of children with asthma." (PMID 36313877, 2022). "Together, these results demonstrate that CLCA1 may be a potential therapeutic target in pediatric asthma." (PMID 36313877, 2022). "CLCA1 was bioinformatically identified as an aberrantly expressed gene in pediatric asthma." (PMID 36313877, 2022). "In this paper, we investigated the expression levels of CLCA1, IL-4, and IL-13 in pediatric asthma." (PMID 36313877, 2022). "CLCA1 is hypothesized to be widely involved in the pathogenesis of inflammatory airway diseases such as asthma." (PMID 36313877, 2022). "Furthermore, previous studies have shown that CLCA1 is an important secretory mediator in asthma, chronic obstructive pulmonary disease, cystic fibrosis, and other diseases that exhibit increased mucus production." (PMID 36313877, 2022). "This study aimed to investigate the role of CLCA1 and IL-13 in pediatric asthma." (PMID 36313877, 2022). "Furthermore, we demonstrated that the expression of IL-13 is highly correlated with CLCA1 in pediatric asthma." (PMID 36313877, 2022). "Using a house dust mite allergen (HDMA)-induced experimental asthma in cynomolgus macaques, CLCA1 was up-regulated in the bronchoalveolar lavage fluid (BALF) as determined by mass spectrometry; and significantly reduced in the same challenged but corticosteroid-treated animals." (PMID 31871532, 2019). "CLCA1 has repeatedly been hypothesized to play a modulatory role in chronic respiratory diseases such as asthma, cystic fibrosis, and chronic obstructive pulmonary disease." (PMID 29610986, 2018). "Members of the CLCA family, especially CLCA1, are known to modulate inflammatory pulmonary diseases such as asthma, COPD, and CF via an as yet unknown mechanism." (PMID 29346439, 2018). "It has been described, together with POSTN and chloride channel accessory 1, as a gene-signature for Th2 asthma and mainly IL-13 asthma phenotype, but until our knowledge, SERPINB2 protein expression has only been studied in broncoalveolar lavage (BAL) and never before at a peripheral level." (PMID 29977241, 2018). "Using microarray profiling of airway epithelial cells, we previously identified a Th2-high molecular phenotype of asthma based on expression of periostin, CLCA1 and serpinB2 and characterized by specific inflammatory, remodeling, and treatment response features." (PMID 23866775, 2013). "In asthma, IL-13 is a key molecule that links CLCA1 expression with mucus production." (PMID 22731784, 2012).
asthma (continued). "Considering the number of assays performed, IL4 showed an excess number of significant SNPs associated with asthma (4 out of 5), while a larger gene such as CLCA1, with 23 SNPs, showed no significant SNP associations." (PMID 21387019, 2011). "Finally, CLCA1 is associated with inflammatory airway disease; however, its role in pediatric asthma had not been reported." (PMID 36313877, 2022). "Together, these data indicate that CLCA1 may play an important role in pediatric asthma." (PMID 36313877, 2022). "Therefore, similar to in asthma, CLCA1 may contribute at least in part to mucus overproduction during fibrosis." (PMID 33066398, 2020). "PRR4, TCN1, CST1, CLCA1, and NOS2 were also highly expressed in patients with asthma in GSE158752 dataset." (PMID 39963184, 2025). "We further used a one-to-one format for comparison and validated with the GSE63142 dataset The genes CEACAM5, PRR4, CPA3, POSTN, TCN1, CST1 (Cystatin-SN), CLCA1, TPSAB1 and NOS2 (Nitric oxide synthase 2) were highly expressed in patients with asthma." (PMID 39963184, 2025). "In their study, the researchers found that asthma patients showed distinct activation of the epithelial genes periostin (POSTN), chloride channel regulator 1 (CLCA1), and serpin peptidase inhibitor clade B member 2 (SERPINB2) when compared to healthy controls." (PMID 41303221, 2025). "The asthma patients were classified into T2-high asthma (n = 22), and T2-low asthma (n = 20) according to the relative expressions of type 2 signature genes, SERPINB2, CLCA1 and POSTN." (PMID 37152983, 2023). "Seventy subjects (28 healthy control subjects and 42 asthma subjects) in datasets GSE4302 underwent unsupervised hierarchical clustering based on the microarray expression levels of SERPINB2, POSTN and CLCA1." (PMID 35550122, 2022). "In dataset GSE4302, subjects with asthma were divided into Th2-high and Th2-low groups according to the expression of the SERPINB2, POSTN and CLCA1 genes." (PMID 35550122, 2022). "CLCA1 is also one of the 6 genes (CLCA1, IL4, IL13, MMP12, TGFB1, TLR4) found in common between our KE genesets and the genesets proposed by Bosse24 for COPD and Poole27 for asthma." (PMID 33731770, 2021). "SERPINB2 along with chloride channel, calcium-activated, family member 1 (CLCA1) and periostin (POSTN), comprise a gene signature for type 2 high asthma." (PMID 34198546, 2021). "The IL-13 response signature (CLCA1, POSTN, SERPINB2) was also upregulated in the central airways in severe asthma compared to health, however, to a lesser extent compared to peripheral airways, and it did not attain significance." (PMID 28045928, 2017). "CLCA1 and SERPINB2 were upregulated in severe asthma and also in peripheral airways suggesting the persistence of the IL-13 signature in this lung region." (PMID 28045928, 2017). "The results were consistent with suggested use of antagonists of A1AR, calcium-activated chloride channel regulator 1 (CLCA1), and epidermal growth factor receptor (EGFR) in asthma treatment." (PMID 29311944, 2017). "Allergic airways inflammation in asthma is characterized by an airway epithelial gene signature composed of POSTN,CLCA1, and SERPINB2." (PMID 28701525, 2017). "Of the three human CLCA proteins, CLCA1 has been identified as a potential biomarker of inflammation and MCM in the airways and suggested as a potential drug target for treatment of asthma and COPD." (PMID 26612971, 2015). "IL-13 stimulation can induce CLCA1 and MUC5AC expression in normal human bronchial epithelial cells and murine asthma models." (PMID 22731784, 2012). "Our results suggest that CLCA1 plays a critical role in COPD by inducing mucus production in the airway epithelia, similar to what is observed in asthma." (PMID 22731784, 2012). "MUC5B, ORMDL3, MUC5AC, CHI3L1, CLCA1, and IL-33 displayed a high non-specific relationship with allergic and nonallergic asthma." (PMID 33936056, 2021).